CTLA4 (cytotoxic T-lymphocyte associated protein 4)
Diseases named in the same sentence as CTLA4 in open-access papers (continued):
Sharing a sentence is not in itself a finding about the gene and the disease.
tumor (continued). "For Braf-mutated tumours, the combination of iBraf + iMek in the first line is challenged by the bi-immunotherapy anti CTLA4 + antiPD1/PDL1, especially for an asymptomatic and slow progressive disease." (PMID 34503304, 2021). "CTLA-4, an immune checkpoint molecule, can suppress T cells multiplication after recognized and differentiated by tumor-associated antigens (TAA) in many cancer including LIHC." (PMID 34790664, 2021). "At the same time, patients with high tumor mutation load are more likely to benefit from anti-CTLA-4 treatment." (PMID 34194437, 2021). "Recent studies have shown that the high burden of copy number loss is positively correlated with anti-PD-1 and anti-CTLA-4 blockade resistance, indicating that copy number loss is closely related to tumor immunity." (PMID 34349753, 2021). "By blocking the inhibitory T cell receptor CTLA-4, anti-CTLA-4 antibodies enhance T cell effector activity, causing tumor regression." (PMID 34376232, 2021). "Apart from MSI, there are other classification systems to stratify patients, such as consensus molecular subtypes, tumour mutation burden (TMB), PD‐1/PD‐L1, CTLA‐4 and tumour immune microenvironment." (PMID 33624434, 2021). "CTLA4-targeted NIR-PIT caused a T-cell mediated antitumor effect in four syngeneic tumor models of cancer and eradiated more than 50% of established tumors." (PMID 34064074, 2021). "Recent studies have described the role of the microbiome in regulating tumour responses to immunotherapies targeting PD-L1 or cytotoxic T-lymphocyte-associated protein 4 (CTLA-4)." (PMID 34357126, 2021). "As an immune checkpoint, cytotoxic T lymphocyte-associated antigen 4 (CTLA-4) plays the key role in tumor immunotherapy." (PMID 34553071, 2021). "It was shown that high-risk patients were likely to profit more from anti-PD1/CTLA4 with the lower potential of tumor immune dysfunction and immune escape." (PMID 34612148, 2021). "Blockade of CTLA-4 with anti-CTLA-4 antibodies enhances priming and activation of naïve T-cells in lymph nodes and then migrate to tumors to cause tumor rejection." (PMID 34966689, 2021). "Abundance of B. fragilis was associated with reduced size of the tumor in the CTLA-4 blockade-treated mice." (PMID 33783613, 2021). "A recent meta-analysis that included 48 trials with 6938 patients receiving either anti-CTLA-4, PD-1, PD-L1 treatments or combination treatments found that tumor histology was associated with the irAE profile." (PMID 34732257, 2021). "Specifically on tumor-infiltrating mononuclear cells, PD-1 and CTLA-4 expression were associated decreased OS, with PD-1 linked to higher tumor grade, tumor stage, and cancer-specific death." (PMID 34831452, 2021). "In particular, it has taken advantage of a tumor panel comprised of 710 tumor-associated genes to reliably calculate TMB in liquid biopsies deriving from 35 melanoma patients treated with ipilimumab (as anti-CTLA-4) and nivolumab (as anti-PD-1)." (PMID 33816298, 2021). "HPV-OPSCC has a different immunophenotype from HPV-negative HNSCC with increased T-cell infiltration, natural killer cells recruitment, PD-L1 and CTLA-4 expression, and higher tumor mutational burden compared to HPV-negative tumors." (PMID 34830871, 2021). "Among different subtypes of immune cells, CD4+ and CD8+ T cells, which play a key role in tumor control, were associated with a significantly lower methylation level in the CTLA4 gene." (PMID 33196890, 2021). "We further explored correlations among the signature-based risk score, tumor mutational burden and levels of PD-1, PD-L1, and CTLA4." (PMID 34925311, 2021). "For example, anti-CTLA4 has been shown to improve T cell responses to tumors associated antigens in the tumor-draining lymph node, the treatment site, and in the distant tumor." (PMID 33816320, 2021). "In gliomas, CTLA-4 overexpression is associated with higher tumour grade and worse clinical outcome." (PMID 33804731, 2021).
tumor (continued). "Overexpression of PD-L1 and CTLA-4 are recognized as a vital suppressor of anti-tumor immunity and associated with better therapy response and increased clinical benefit." (PMID 34088360, 2021). "It has been shown that ICOS-deficient mice displayed attenuated anti-tumor T cell responses to anti-CTLA-4 therapy." (PMID 33602280, 2021). "In 1996, they demonstrated that the in vivo administration of antibodies against CTLA-4 (cytotoxic T-lymphocyte-associated protein 4) resulted in tumor rejection, and was termed the so-called “checkpoint blockade immunotherapies”." (PMID 34503236, 2021). "Nivolumab is a monoclonal antibody that can inhibit programmed death 1 (PD-1) and Ipilimumab is a monoclonal antibody against CTLA-4(cytotoxic T lymphocyte-associated antigen 4), both of which can prevent the immune escape of tumor cells." (PMID 34391428, 2021). "ICIs selectively restore and normalize the body’s immune responses by disrupting the immunoinhibitory signals mediated by PD-1, PD-L1 and cytotoxic T-lymphocyte-associated protein 4 (CTLA-4) in the tumor microenvironment." (PMID 34135884, 2021). "We showed that co-injection of myCAF and tumour cells causes CD8 T-cells to accumulate at the tumour periphery in a mechanism that is, at least in part, regulated by CTLA4 upregulation on the CD8 T-cells." (PMID 34262652, 2021). "Treg cells, which expressed CTLA-4, were also more enriched in the high-risk group and played a vital role in inhibiting anti-tumor immune responses." (PMID 33568167, 2021). "In contrast, the combination of nivolumab with the anti-CTLA-4 blocking antibody ipilimumab improved PFS in patients with high tumor mutational burden compared to standard chemotherapy." (PMID 32767058, 2021). "Cancer cells are able to evade anti-tumor response by overexpressing immunosuppressive molecules such as cytotoxic T-lymphocyte associated antigen 4 (CTLA-4), programmed cell death protein (PD-1), and its ligand PD-L1." (PMID 33381178, 2020). "Immune cells are thought to be inactivated in tumor microenvironment, via the engagement of inhibitory receptors such as the famous Cytotoxic T-Lymphocyte Associated Protein 4(CTLA4) and Programmed cell death protein 1 (PD-1)." (PMID 33208183, 2020). "It was reported that a high baseline expression of FoxP3+ Tregs in the tumor is positively associated with better survival in a retrospective study involving patients under the treatment of anti-CTLA-4 antibodies." (PMID 33194652, 2020). "Immune checkpoint inhibitors directed against cytotoxic T-lymphocyte-associated protein 4 (CTLA-4) and programmed cell death protein-1 (PD-1) on T-cells, facilitate immune recognition of tumor neo-antigens and immune-mediated tumor control." (PMID 33202676, 2020). "In tumor pathophysiology, the binding between PD-1 on T cells and PD-L1 on cancer cells, or between CTLA-4 on T cells and B7 on tumor cells, causes the escape/evasion of the tumor from the immune response and supports the growth of malignant cells." (PMID 33167582, 2020). "The tumor cells use mechanisms such as the up-regulation of immune checkpoint signaling program (PD-L1, CTLA-4), the blockage of co-stimulation to activate T cells, and the recruitment of MDSCs, and tumor-associated macrophages to achieve immune suppression." (PMID 32493354, 2020). "When compared to wild type animals, mice carrying the Foxp3fgfp allele spontaneously delay, reduce or prevent primary tumor growth, decrease metastasis growth, and potentiate the response to anti‐CTLA4 monotherapy." (PMID 31729760, 2020). "Subsequently, uni- and multi-variate Cox analyses found that some variables, including CTLA4, age, tumor pathological grade and stage, were independent risk factors in ccRCC (p < 0.01)." (PMID 33117084, 2020). "Dexamethasone has been shown to lead to the upregulation of the immunosuppressive checkpoint cytotoxic T-lymphocyte-associated protein 4 (CTLA-4) on the surface of T cells, thereby reducing their anti-tumor activity." (PMID 33178210, 2020).
tumor (continued). "CPIs target negative immune checkpoint molecules, including PD-1, PD-L1, and CTLA-4, which causes an increased immune response and decreased tumor progression." (PMID 32823814, 2020). "Depletion of CD206high TAMs and reprogramming of the others, when combined with immune checkpoint blockade with PD-1 or cytotoxic T-lymphocyte-associated protein 4 (CTLA-4) antagonists, improved the anti-tumor immunity." (PMID 32370075, 2020). "Tumor cells activate immune checkpoints such as molecular programmed death receptor-1 (PD-1) and cytotoxic T lymphocyte-associated antigen 4 (CTLA-4) pathways." (PMID 33261023, 2020). "The tumor mutational burden (TMB) has been shown to correlate with patient response to both CTLA-4 and PD-1 inhibition in several tumor types." (PMID 32240238, 2020). "The inhibition of immune checkpoints, such as programmed death-1 (PD-1) or cytotoxic T-lymphocyte-associated protein-4 (CTLA-4), have led to a breakthrough in cancer treatment by releasing the break on cellular anti-tumor immunity." (PMID 32455836, 2020). "Overall, characterization of the tumor infiltrated microenvironment supports the idea that there are different patterns of tumor immune response associated with CTLA-4 expression levels and activated-like status in tumor-cells." (PMID 32850353, 2020). "In contrast, FUT4-overexpressing PTCs were associated with up-regulation of CTLA-4, PD-1, and PD-L1 in the tumor microenvironment that is known to exert immunosuppressive and pro-tumorigenic activities." (PMID 32486143, 2020). "In pancreatic ductal adenocarcinoma (PDAC), CTLA-4+ Tregs infiltrate tumor tissue relatively early and these cells tend to be predominantly redistributed to lymph nodes surrounding the tumor, which is associated with progression of the disease." (PMID 32488850, 2020). "The two first targetable checkpoint receptors in tumor microenvironment discovered were cytotoxic associated lymphocyte antigen-4 (CTLA-4) and programmed death-1 (PD-1)." (PMID 33194687, 2020). "The well-known immune checkpoints inhibitors (ICIs) targeting the programmed cell death 1 (PD-1) or the cytotoxic T-lymphocyte associated antigen 4 (CTLA-4) checkpoints have demonstrated the potential for relatively tumor-specific immune disinhibition." (PMID 32168869, 2020). "Many tumor cells over-express a ligand, the programmed death-ligand 1 (PD-L1), which binds inhibitory receptors expressed on T lymphocytes, such as cytotoxic T lymphocyte-associated protein-4 (CTLA-4) and programmed death protein-1 (PD-1)." (PMID 32676031, 2020). "The PD-L1 is expressed by the tumor cells as well as immune cells such as antigen presenting cells (APCs) and tumor-associated macrophages (TAMs) while CTLA-4 is mainly expressed by activated T-cells such as memory T-cells and regulatory T-cells." (PMID 32961872, 2020). "The inhibitory checkpoints, such as programmed cell death ligand-1 (PD-L1) and cytotoxic T lymphocyte associated antigen 4 (CTLA4) have been demonstrated to inhibit anti-tumor immunity, leading to evade the host immune attack." (PMID 33520701, 2020). "Various studies have demonstrated that anti-tumor T cell responses in mice can be significantly boosted by combining cytotoxic T lymphocyte-associated antigen 4 (CTLA-4) blockade with ICOS engagement." (PMID 33033255, 2020). "In a preclinical mouse model, targeting of chemokine ligand 12 (CXCL12) improved antitumor immunity and caused tumor reduction via T cell activity and upregulation of PD-L1 and CTLA-4, highlighting the role of CXCL12 in immune response evasion." (PMID 33050151, 2020). "Similar findings have shown that CTX given after CTLA-4 blockade in a CT26 colon model can attenuate its effects by causing apoptosis of highly proliferative tumor specific CD8+ T cells." (PMID 32704531, 2020).
tumor (continued). "CTLA-4 blockade appears to broaden blood CD8+ T cell responses against tumor associated antigens, increasing the number of tumor-specificities measured by peptide-MHC multimer staining when pre- and post-blood samples were compared." (PMID 33163002, 2020). "CTLA-4 is a co-inhibitory receptor associated with suppression of anti-tumor immune responses and has a higher affinity than CD28 for binding CD80." (PMID 31959281, 2020). "Immune checkpoint inhibitors targeting these molecules, notably cytotoxic T-lymphocyte-associated protein 4 (CTLA-4), programmed death-1 (PD-1), and its ligand programmed death-ligand 1 (PD-L1), have been developed to block the tumor-induced immunomodulation." (PMID 33194476, 2020). "A study in CTLA-4-deficient animals demonstrated the pivotal role of CTLA-4 in halting T-cell-mediated immune anti-tumor activity." (PMID 32357515, 2020). "The CTLA-4 blockage can increase T cell stimulation and activity to continually attack tumor cells, but it often causes a range of immune-related adverse events such as rash, hepatitis and even enterocolitis that sometimes requires a colectomy." (PMID 32586313, 2020). "PD-1 and CTLA4 levels were significantly associated with tumor purity in 35 and 36 cancer types, respectively." (PMID 33072070, 2020). "ICIs augment T-cell mediated anti-tumor responses, most commonly via programmed cell death 1 (PD-1) and cytotoxic T-lymphocyte-associated antigen-4 (CTLA-4) pathways." (PMID 33598436, 2020). "The discovery made by Prof. Allison’s group showing in murine model of tumor that the blocking of CTLA-4 caused an enhanced antitumor immunity, gave a new perspective on therapeutic approaches to cancer." (PMID 33519815, 2020). "Recently, the association between immunological parameters in tumor tissues at baseline and the clinical activity of anti-CTLA-4 therapy has been explored." (PMID 32194568, 2020). "For example, primary resistance to anti-CTLA-4 therapy can be caused by the inability of the major histocompatibility complex (MHC) to recognize tumor-associated antigens." (PMID 32316916, 2020). "In melanomas, high tumor mutational burden (TMB) is a critical prognostic marker for anti-CTLA-4 treatment." (PMID 32117295, 2020). "A2AR blockade and programmed death-1 (PD-1)/cytotoxic T-lymphocyte–associated antigen 4 (CTLA-4) monoclonal antibody (mAb) combined therapy also illustrated impressive effects in a variety of syngeneic tumor models." (PMID 32280302, 2020). "This antibody is directed at cytotoxic T lymphocyte-associated antigen-4 (CTLA-4), programmed cell death 1 (PD-1), and programmed cell death 1 ligand 1 (PD-L1) receptors; it initiates immune cell function, and normalizes the tumor microenvironment." (PMID 33282564, 2020). "Ipilimumab is a monoclonal antibody (mAb) that targets Cytotoxic T Lymphocyte Associated Protein 4 (CTLA-4), inhibiting its actions as a suppressive immune checkpoint and thereby facilitating an anti-tumour immune response." (PMID 33148287, 2020). "Monoclonal antibodies (mAb) blocking programmed cell death-1 (PD-1), its ligand PD-L1, or cytotoxic T lymphocyte-associated protein-4 (CTLA-4) augment tumor-reactive cytotoxic T cell function and are currently FDA-approved treatments for several cancers." (PMID 32020483, 2020). "CTLA4 expression was positively related to dendritic cells (cor = 0.446, P = 1.32E-23) and negatively associated with tumor purity (cor = −0.267, P = 5.51E-09)." (PMID 33014010, 2020). "All together, these data provide a rationale for the combination of PARPi with anti-CTLA-4 in BRCA-deficient tumours." (PMID 32526888, 2020). "In mice and patients, T cell responses specific for B. thetaiotaomicron or B. fragilis were associated with the efficacy of CTLA-4 blockade through induction of Il-12-dependent Th1 anti-tumor responses." (PMID 32916853, 2020).
tumor (continued). "This role in host defense is fulfilled by CD8+ T cells, making them preferentially susceptible to CTLA-4 and PD-1 upregulation after exposure to tumor antigen." (PMID 33584650, 2020). "In order to escape detection by the immune system, tumor cells upregulate the surface expression of inhibitory molecules, including PD-L1, cytotoxic T-lymphocyte associated protein 4 (CTLA-4), LAG-3, TIM-3, and 4-1BB." (PMID 31963413, 2020). "The administration of belinostat was reported to induce CTLA-4 inhibition, which was responsible for M1-phenotypic tumour-associated macrophages (TAMs), and decrease splenic regulatory T cells (Tregs)." (PMID 32340605, 2020). "The development of immune checkpoint therapies is an effective strategy to enhance anti-tumor immune responses of T-cells, for example using antibodies against cytotoxic T-lymphocyte-associated protein 4 (CTLA-4) or programmed cell-death 1 (PD-1)." (PMID 32647818, 2020). "We evidence reduced primary tumor growth associated with increased immune responses, reduced metastatic progression, and enhanced response to anti‐CTLA4 monotherapy in Foxp3‐fGFP mice when compared to WT controls." (PMID 31729760, 2020). "CTLA4 expression was positively related to dendritic cells and negatively associated with tumor purity, indicating that CTLA4 has significant roles in immune infiltration cells in ccRCC." (PMID 33014010, 2020). "Here, the authors integrated data from mutational profile and tumor infiltrating cells in 113 advanced patients treated with anti CTLA-4/PD-1." (PMID 32365882, 2020). "In particular, they showed that EZH2 is upregulated upon anti-CTLA-4 or IL-2 immunotherapies in cancer cells, leading to a loss of tumor control." (PMID 32042336, 2020). "For example, STAT3 increased CTLA-4 expression in tumor-associated B cells in a JAK-dependent manner and enhanced CTLA-4 expression in Treg cells through IL-10." (PMID 32972405, 2020). "Blocking of inhibitory receptors, such as programmed death-1 (PD-1) or cytotoxic T-lymphocyte-associated antigen 4 (CTLA-4), on T-cells, or their ligands on tumor or adjacent T-cells, potentiates anti-tumor responses." (PMID 33353234, 2020). "Further analysis according to the TIMER database demonstrated that CTLA4 expression was positively related to dendritic cells (cor = 0.446, P = 1.32E-23) and negatively associated with tumor purity (cor = −0.267, P = 5.51E-09)." (PMID 33014010, 2020). "Syngeneic tumor models are also used to investigate the antitumor activity of ICIs, including anti-cytotoxic T lymphocyte-associated antigen-4 (CTLA-4) and anti-programmed death (PD)-1 anti-PD-L1 antibodies." (PMID 32526987, 2020). "Tumor responses to these therapies are mediated mainly by anti-tumor T cell immunity previously blocked by CTLA-4 (cytotoxic T lymphocyte-associated protein 4) or PD-1 (programmed cell death 1)." (PMID 31602274, 2019). "The reinvigorated anti-tumor immunity resulting from the coincident blockade of the programmed cell death protein-1 (PD-1) and cytotoxic T lymphocyte-associated protein 4 (CTLA-4) has triggered much interest in combination therapies." (PMID 31189114, 2019). "In vitro studies of anti-CTLA-4 monoclonal antibodies with the same IgG1 and IgG2 Fc variants such as ipilimumab and tremelimumab exhibited superior tumor killing with antibodies able to maximize T-reg depletion by ADCC." (PMID 30941125, 2019). "A notable mechanism of immune evasion involves tumor cell signaling to the checkpoint of programed cell death-1 (PD-1) and cytotoxic T-lymphocyte-associated antigen 4 (CTLA4) receptors of CD8+ T-cells." (PMID 31795835, 2019). "The expression of TIM-3 as a marker of T cell exhaustion in association with other tumor-associated T-cell exhaustion markers (e.g., PD-1, CTLA-4) has led to its investigation as a target for cancer immunotherapy." (PMID 30788290, 2019).